FAM138A (family with sequence similarity 138 member A)
Synonyms: F379
Gene: Long non-coding RNA gene on chromosome 1 (34,553 to 37,595, reverse strand). Ensembl gene ENSG00000237613.
Homologues: Paralogues in human: FAM138F (100% identical).
Diseases named in the same sentence as FAM138A in open-access papers:
FAM138A is named in the same sentence as 1 disease in open-access papers, as found by Europe PMC text mining. Sharing a sentence is not in itself a finding about the gene and the disease.
FAM138A shares sentences with these, for which no sentence is quoted: cancer (1 paper).